ZMIZ1 (zinc finger MIZ-type containing 1)
Diseases named in the same sentence as ZMIZ1 in open-access papers (continued):
Sharing a sentence is not in itself a finding about the gene and the disease.
triple-negative breast carcinoma (1 paper, 2024). An invasive breast carcinoma which is negative for expression of estrogen receptor (ER), progesterone receptor (PR), and human epidermal growth factor receptor 2 (HER2). "Analysis of two ER-positive (MCF7 and T47D) and one triple negative breast cancer (TNBC) model (MDA-MB-231) showed that knockdown of ZMIZ1 reduced cell proliferation in all three cell lines (ANOVA, P< 0.001)." (PMID 38564418, 2024).
uterine cancer (1 paper, 2025). Primary or metastatic malignant neoplasm involving the uterine corpus and/or the cervix. "Since uterine cancer is also estrogen sensitive, we evaluated uterine corpus endometrial cancer samples (UCEC) in TCGA for the impact of the relative level of ZMIZ1 transcript expression on survival using the UALCAN tool." (PMID 41321316, 2025).
uterine tumors (1 paper, 2025). "First, using cBioportal analysis of The Cancer Genome Atlas (TGCA) data, we found that ZMIZ1 mutations occur in up to 14% of uterine tumors." (PMID 41321316, 2025).
Wilms tumor (1 paper, 2023). An embryonal neoplasm characterized by the presence of epithelial, mesenchymal, and blastema components. "Another study examined the link between the expression of ZMIZ1 and Wilms tumor due to the fact that ZMIZ1 is associated with cancer etiology with unknown specific function in tumor development and progression." (PMID 37047552, 2023).
cancer (15 papers, 2020 to 2025). A tumor composed of atypical neoplastic, often pleomorphic cells that invade other tissues. "These cohort studies suggest that the expression of ZMIZ1 is closely associated with cancer progression, and further affects patient prognosis." (PMID 38214831, 2024). "In cancer biology, ZMIZ1 has been implicated as a potential oncogene." (PMID 41321319, 2025). "Among them, ZMIZ1 is a transcriptional coactivator with established roles in development, immune regulation, and cancer progression." (PMID 41321319, 2025). "Overall, ZMIZ1 plays a critical role in cancer initiation and progression, but studies on its specific molecular functions and regulatory mechanisms are still in their infancy." (PMID 38214831, 2024). "Mounting evidence suggests that ZMIZ1 plays a crucial role in the occurrence and development of cancers." (PMID 38866828, 2024). "We characterise ZMIZ1 function by demonstrating a significant decrease in the proliferation of ER-positive cancer cell lines." (PMID 38564418, 2024). "In conclusion, even in different types of solid tumors, ZMIZ1 exerts significant pro-carcinogenic effects and even drives carcinogenesis, and its targeting would be beneficial in hindering cancer." (PMID 38214831, 2024). "Both knockdown and pharmacological inhibition of SIRT1 neutralized the effects of ZMIZ1 knockdown on cancer cells." (PMID 38214831, 2024). "suggest that ectopic expression of ZMIZ1 induces cutaneous squamous cell malignancy in a mouse model of cancer." (PMID 38214831, 2024). "On the basis of these results, we tested the hypothesis that knockdown of the ZMIZ1 protein would result in reduced proliferation of ER-positive cancer cell line models." (PMID 38564418, 2024). "The specific molecular functions of ZMIZ1, as well as its specific mechanisms involved in cancer progression remain completely unknown." (PMID 38214831, 2024). "Together, these studies suggest that ZMIZ1 might act as a direct transcriptional co-factor for Notch1, and disrupting the Notch1-ZMIZ1 interaction may impact upon tumorigenesis, proliferation and metastasis in various cancers." (PMID 38866828, 2024). "ZMIZ1, a novel HIF-1α co-activator, has been shown to promote metastasis in cancer." (PMID 39334513, 2024). "In addition, separation between LCH cells and other lesion MNPs was also evident on the regulatory network level, that revealed neoplasm/cancer related regulons specifically active in LCH cells (ERG1, ETV5, ZMIZ1)." (PMID 36525505, 2022).
tumor (13 papers, 2014 to 2025). "Additionally, our findings highlighted the association of ZMIZ1 with key factors involved in tumor progression, such as MMP7, MKP-1, and SSBP2, underscoring its multifaceted impact on TSCC biology." (PMID 38866828, 2024). "Further, the distribution of ER and ZMIZ1 staining correlated, implicating that ER and ZMIZ1 are expressed within the same cells of the patient tumours." (PMID 38564418, 2024). "Expression levels of Jagged1, MKP-1, MMP7, Notch1, SSBP2, and ZMIZ1 in tumor tissues of LV-ZMIZ1-RNAi CAL-27 mice were decreased compared to the control group (P < 0.05)." (PMID 38866828, 2024). "We knocked down ZMIZ1 in TSCC tumor cells and investigated the impact on TSCC invasion and metastasis in vitro and in vivo." (PMID 38866828, 2024). "In conclusion, we establish that ZMIZ1 is a regulator of the estrogenic cell cycle response and provide evidence of the biological importance of the ER–ZMIZ1 interaction in ER-positive patient tumours, supporting potential clinical relevance." (PMID 38564418, 2024). "To further validate the link between ER and ZMIZ1, we checked if ZMIZ1 expression was found in the ER-positive tumour cells in clinical material." (PMID 38564418, 2024). "ZMIZ1 gene body hypermethylation inhibits tumour cell migration by regulating variable splicing and reducing the expression level of transcripts with higher potency, so patients with ZMIZI gene body hypermethylation tend to have a better prognosis." (PMID 36443876, 2022). "Next, we assessed anchorage-independent growth as an in vitro surrogate for the earliest stages of tumor development in HaCaT cells stably transduced with empty vector, full-length ZMIZ1 or ZMIZ1 ΔN185." (PMID 34398873, 2021). "To corroborate these findings in the Zmiz1 model, we examined squamous skin tumors from another tumor study in aging mice, and these tumors followed a similar biological progression." (PMID 25309748, 2014). "In glioblastoma, the ZMIZ1 gene is a driver of tumour cell migration." (PMID 36443876, 2022). "ZMIZ1 protein expression appeared to be abundant within the TSCC tumor tissue, but weakly expressed in adjacent non-tumor tissue." (PMID 38866828, 2024). "Further, we were able to show that within patient samples where ZMIZ1, ER and KI67 protein expressions correlated, ZMIZ1 expression is predictive of survival, and the proteins are both localised within the nuclei of patient tumour cells." (PMID 38564418, 2024). "ZMIZ1 knockdown reduced the invasion and metastases of TSCC tumor cells and promoted apoptosis." (PMID 38866828, 2024). "We hypothesized that tumors without activating oncogenic insertions in the Zmiz1 or Zmiz2 genes would have higher frequencies of inactivation of the tumor suppressor genes found in the Onc2.3 system." (PMID 33435458, 2021).
neurodevelopmental disorder (7 papers, 2021 to 2025). A behavioral and cognitive disorder with onset during the developmental period that involves impaired or aberrant development of intellectual, motor, or social functions. "Among which, ZMIZ1 was associated with neurodevelopmental disorders with dysmorphic facies and distal skeletal abnormalities (NEDDFSA, OMIM #618659)." (PMID 40044118, 2025). "Among which, ZMIZ1 was associated with neurodevelopmental disorders with dysmorphic facies and distal skeletal abnormalities, which was consistent with the phenotype of pregnant women." (PMID 40044118, 2025). "Currently, 32 patients with neurodevelopmental disorders have reported carrying pathogenic variants in the protein coding sequences of ZMIZ1 (n = 29) and chromosomal translocations involving ZMIZ1 (n = 3)." (PMID 35432459, 2022). "Zinc Finger MIZ-Type Containing 1, or ZMIZ1, is a transcriptional co-activator known to interact with the androgen receptor, and its nucleotide variants have been associated with neurodevelopmental disorders." (PMID 33940396, 2021). "From this group of studies reporting ZMIZ1 variants associated with developmental and neurodevelopmental disorders (36 cases), we selected those that included in-depth neurological and physical phenotypical descriptions of individuals for further analysis (21 cases)." (PMID 40529245, 2025). "It has been reported that ZMIZ1 could cause the occurrence of a rare neurodevelopmental disorder, neurodevelopmental disorder with dysmorphic facies and distal skeletal anomalies (NEDDFSA)." (PMID 35432459, 2022). "In the same year of 2019, an affected father and his two sons were identified to be suffering from the ZMIZ1-related neurodevelopmental disorder in Florida." (PMID 35432459, 2022). "Zmiz1 was shown to play a key role in neural development in a syndromic neurodevelopmental disorder." (PMID 33628784, 2021). "Since there was no experimental evidence for KLHL29 leading to neurodevelopmental disorder, ZMIZ1 was considered as the most potential disease-causing gene." (PMID 35432459, 2022). "Pathogenic variants of the zinc finger MIZ-type containing 1 (ZMIZ1, OMIM#607159) could cause the occurrence of a rare syndromic disease, neurodevelopmental disorder with dysmorphic facies and distal skeletal anomalies (NEDDFSA) with an autosomal dominant (AD) mode of inheritance." (PMID 35432459, 2022).
infection (1 paper, 2025). The state of being infected such as from the introduction of a foreign agent such as serum, vaccine, antigenic substance or organism. "We found that the transcription factor, GATA4, was highly regulated by Ad‐Zmiz1 infection in chondrocytes." (PMID 40040621, 2025). "GSEA revealed that the gene set up‐regulated by Ad‐Zmiz1 infection was positively related to a previously reported OA gene signature." (PMID 40040621, 2025). "Mmp3 and Cox2 expression were increased in IL‐1β‐treated chondrocytes with Ad‐Zmiz1 infection, compared to the corresponding non‐infected chondrocytes." (PMID 40040621, 2025). "Given that chondrocyte dedifferentiation, which is marked by the loss of anabolic factor expression, leads to chondrocyte senescence, we also assessed the mRNA expression levels of the major anabolic factors, Col2a1, Acan, and Sox9, and found that they were decreased by Ad‐Zmiz1 infection." (PMID 40040621, 2025).
primary dysmenorrhoea (1 paper, 2017). "Here, Li and colleagues identify common variants in ZMIZ1 and near NGF conferring risk for primary dysmenorrhoea using genome-wide association study in a Chinese population." (PMID 28447608, 2017). "Previous researches demonstrated obvious immunological functions for both ZMIZ1 and NGF, suggesting a potential role for the immune system in the pathogenesis of primary dysmenorrhoea." (PMID 28447608, 2017). "In summary, we present the first GWAS for primary dysmenorrhoea in Chinese population and identify two GWS loci (ZMIZ1 and NGF)." (PMID 28447608, 2017).
psychiatric disorder (1 paper, 2024). A disorder characterized by behavioral and/or psychological abnormalities, often accompanied by physical symptoms. "Therefore, with respect to Prox1 and beyond, examining the role of Zmiz1 in hippocampal neurogenesis and subsequent neural identity specification, connectivity, and pathological association with neurological and psychiatric disorders may provide new insights into this important topic." (PMID 38718095, 2024).
ZMIZ1 also shares sentences with these, for which no sentence is quoted: glioblastoma (3 papers); inflammatory bowel disease (3); astrocytoma (2); attention deficit-hyperactivity disorder (2); bladder cancer (2); Neurodevelopmental delay (2); neurologic disorders (2); systemic lupus erythematosus (2); ulcerative colitis (2); Alzheimer disease (1); amyloid (1); Anxiety (1); behavioral disorders (1); capillary malformation (1); cognitive deficits (1); diseases of the endometrium (1); fibroids (1); Hirschsprung disease (1); keratoacanthoma (1); lung adenocarcinoma (1); lupus nephritis (1); migraine (1); neurodegenerative disease (1); osteoporosis (1); primary biliary cirrhosis (1); rheumatoid arthritis (1); seizure disorders (1); speech development delay (1); T-cell acute lymphoblastic leukemia (1); uterine disorder (1).